XBP1 (X-box binding protein 1)
Diseases named in the same sentence as XBP1 in open-access papers (continued):
Sharing a sentence is not in itself a finding about the gene and the disease.
tumor (continued). "IRE1/XBP1 signaling is activated in malignant tumors and plays numerous roles in tumor growth and aggressiveness." (PMID 33746610, 2021). "Taken together, miR-214 acts to suppress HCC progression as it inhibits proliferation, tumour growth, angiogenesis, and metastasis through targeting XBP1, β-catenin, HDGF and FGFR-1." (PMID 34943783, 2021). "XBP1 deletion impaired angiogenesis and combined treatment with RNA NPs and doxorubicin (dox) can further impair tumor angiogenesis and down-regulate HIF1α target expressions." (PMID 33413427, 2021). "In this study, we identified a novel role of XBP1 as a tumor promoter in the tumorigenesis and tumor progression of NSCLC." (PMID 34094948, 2021). "Conditional deletion of XBP1 in TAMs significantly inhibited tumor formation in AOM-DSS mouse model." (PMID 34667145, 2021). "PERK and XBP1 are the main branch of ER membrane proteins that can modulate tumor cell migration and invasion features such as ECM and EMT." (PMID 34066056, 2021). "Our study reveales a new mechanism of XBP1 in TAMs that promotes phagocytosis of tumor cells by disrupting self-recognition." (PMID 34667145, 2021). "This prevents miR-214-mediated tumour suppression and XBP1 downregulation, thus encouraging HCC progression." (PMID 34943783, 2021). "Specifically, XBP1 signaling regulates the lipid metabolism and antigen presentation of tDCs, while silencing XBP1 in tDCs extends host survival by enhancing T cell anti-tumor immunity." (PMID 34660599, 2021). "XBP1 inhibition promoted macrophage phagocytosis of tumor cells by disturbing the self-recognition of TAMs." (PMID 34667145, 2021). "Several functional studies have shown that targeting the expression or RNase activity of IRE1 reduces tumor progression by suppressing the XBP1-mediated survival effect on tumor growth." (PMID 33746610, 2021). "Accordingly, XBP1 expression was correlated to cancer stem cell expansion and tumor relapse post therapy." (PMID 33842465, 2021). "Further IHC analysis showed IGFBP3 is also highly expressed in NSCLC tumor tissues and is positively correlated with the expression of XBP1 expression." (PMID 34094948, 2021). "In summary, our current work revealed XBP1 is a novel biomarker of NSCLC, which was closely associated with tumor lymph node metastasis, advanced clinical stages and poor prognosis." (PMID 34094948, 2021). "Inhibition of XBP1 in TAMs downregulated the expression of pro-tumor cytokines, such as IL-4, IL-6, MMP2 and VEGFA." (PMID 34667145, 2021). "Inhibition of XBP1 splicing by IRE1α inhibitor 4μ8c also diminished tumor-promoting function of TAMs (Ana-1 conditioned medium [CM])." (PMID 34667145, 2021). "Altogether, these data suggest a dual role of IRE1 RNase function in tumor development depending on the prevalence of XBP1 splicing or RIDD activity." (PMID 33842465, 2021). "ERS is commonly believed to affect natural killer (NK) cell-dependent tumor recognition, and NK cells are mainly regulated and recruited by IRE1α–XBP1 signaling and mediate bladder cancer cell differentiation or death." (PMID 34136492, 2021). "XBP1 regulates TNBC anchorage-independent growth and invasiveness to promote tumorigenicity, tumor progression, and recurrence, a significant role for XBP1 in regulating the HIF1α transcriptional program." (PMID 33746610, 2021). "In contrast, cholesterol in tumor tissues induced the expression of XBP1 in tumor-infiltrating CD8+ T cells." (PMID 34660599, 2021). "Ablation of XBP1 inhibited the expression of the pro-tumor cytokine signature of TAMs, including IL-6, VEGFA, and IL-4." (PMID 34667145, 2021). "This is consistent with Romero-Ramirez and colleagues who demonstrated the importance of XBP1 in tumour survival." (PMID 34943783, 2021). "This was also shown by the total UPR expression profile and post cell-treatment with GSK2606414, which revealed the suppression of major UPR driver genes, including IRE1 (ERN1) and XBP1, which are key players in MM tumor growth." (PMID 33028016, 2020).
tumor (continued). "The ER stress sensor IRE1α contributes to tumor progression through XBP1 mRNA splicing and regulated IRE1α-dependent decay of mRNA and miRNA." (PMID 32576923, 2020). "XBP-1 regulates unfolded protein response (UPR) and both UPR and XBP-1 are essential for tumor growth under hypoxic stress and glucose deprivation." (PMID 33322508, 2020). "Accordingly, DC-specific XBP1 inhibition restores their immunostimulatory capacity and extends survival in tumor-bearing mice." (PMID 32850317, 2020). "By suppressing the XBP1 transcriptional capacity or reducing cholesterol content in the microenvironment, the anti-tumor activity of CD8+ T cells can be restored." (PMID 32486083, 2020). "Similar studies have also demonstrated that cytokines in the tumor microenvironment, such as IL-4, IL-6, and IL-10, can activate the IRE1α-XBP1 branch." (PMID 33267910, 2020). "The ratio of spliced to unspliced Xbp1-mRNA was significantly increased in the surrounding non-tumor tissue of DEN-induced mice." (PMID 33103995, 2020). "Our data showed that XBP1 was overexpressed in GBC tissues compared with matched adjacent non-tumor tissues." (PMID 32793479, 2020). "We also analyzed the associations of CCDC170, IRE1 and XBP1 mRNA levels with clinicopathologic characteristics such as ERα, progesterone receptor (PR), Her2 and Ki67 levels, the PAM50 subtype, tumor size, lymph node status and TNM stage in TCGA and GEO." (PMID 33291081, 2020). "In SMM a multi-peptide vaccine PVX-140 has been designed to induce a T cell mediated immune response by specifically stimulating CTLs with the tumor antigen targets X-box binding protein 1 (XBP1), Syndecan-1 (CD138), and SLAMF7 (CS1)." (PMID 32432039, 2020). "Motivated by these findings, we further explored the effect of the IRE1α–XBP1 pathway on the anti-tumor activity against MM by using the novel ‘mono’-specific inhibitor of IRE1α, KIRA8, in this study." (PMID 32878237, 2020). "In summary, hijacking and upregulation of the IRE1α-XBP1 pathway is one strategy tumor cells use to develop chemoresistance, yet further investigation is required on the detailed mechanisms about how this pathway is activated and how it leads to resistance." (PMID 32850317, 2020). "Conditional knockout mice harboring XBP1 deletion in dendritic cells were strongly protected against tumor growth compared to WT mice." (PMID 32178254, 2020). "DC-specific siRNA silencing of XBP1 led to decreased lipid accumulation by DCs and enhanced immune-mediated tumor control in mouse models of ovarian cancer." (PMID 32508825, 2020). "Having established that XBP1 splicing occurs in tumor-infiltrating CD11b+ cells, we sought to detect other features of the IIS phenotype." (PMID 32520957, 2020). "Gm40600 reduced SP 2/0 cell proliferation and isograft tumor growth and progression by suppressing Blimp1 and Xbp1-mediated Bcl2 transcription to induce apoptosis." (PMID 31311517, 2019). "Many researches have already demonstrated that transcriptional activation of XBP1 contributes to tumor growth." (PMID 30783083, 2019). "Overall, the upregulation of PRKCSH in tumor tissues suggests a molecular rationale for altered IRE1α–XBP1 signaling in and adaption of tumor cells to ER stress." (PMID 31320625, 2019). "In contrast, tumor dendritic cells with inactivated XBP-1 are accessible to strengthen the functions of T lymphocytes, such as maturation of cytotoxic T lymphocytes and memory T lymphocytes, without the aberrant accumulation of intracellular triglycerides." (PMID 31121863, 2019). "Curiously, ovarian cancer cells have been shown to be capable of inducing the IRE1α-XBP1 arm in T cells to decrease their anti-tumor activity via suppressing mitochondrial respiration and interferon gamma (IFNγ) production." (PMID 31491919, 2019). "MKC-3946-driven tumor cell apoptosis is using blocking XBP1 mRNA splicing and increasing the expression of CHOP." (PMID 31121863, 2019).
tumor (continued). "Patient-derived TNBC cells transplanted into mice form fewer tumors when XBP1 was depleted, while patient-derived TNBC cells form more tumors when XBP1 was overexpressed, suggesting that XBP1 is important for TNBC tumor initiation and progression." (PMID 31739582, 2019). "Using these pulse doses, we measured the level of spliced XBP1 mRNA in both nsPEF-treated tumor cell lines." (PMID 31861079, 2019). "TNBC cells injected into mice have been demonstrated to develop resistance to chemotherapeutic drugs, doxorubicin and paclitaxel, while XBP1 depletion has been shown to attenuate the resistance and tumor recurrence." (PMID 31739582, 2019). "Several studies demonstrated that inhibition of the expression or the RNase activity of IRE1 suppresses the development of several types of tumours, mostly because of the ablation of pro-survival effects of XBP1 on tumour growth." (PMID 31572192, 2019). "Work from the Cubillos-Ruiz and Glimcher groups has investigated the role of XBP1, the main transcription factor downstream the IRE1α pathway, in tumor-infiltrating DCs and T cells." (PMID 31690657, 2019). "Further, the activation of NF-κB and p38 MAPK signaling and gene expression of several components of UPS and autophagy were reduced in skeletal muscle of XBP1-knockout mice compared to controls in response to LLC tumor growth." (PMID 31817027, 2019). "XBP1 is one of the most important ER-stress related gene that are involved in tumorigenesis and metastasis of tumor cells." (PMID 30783083, 2019). "Overexpression of Gm40600 suppressed SP 2/0 cell proliferation and isograft tumor growth by reducing Blimp1 and Xbp1-mediated transcription of the anti-apoptosis molecule Bcl2." (PMID 31311517, 2019). "Increased levels of PRKCSH in various tumor tissues are positively correlated with the expression of XBP1-target genes." (PMID 31320625, 2019). "In numerous tumors, IRE1α–XBP1 signaling has cytoprotective activity, allowing tumor cells to adapt to ER stress." (PMID 31320625, 2019). "Silencing of Ire1 or depletion of Xbp1 transforms DCs into immunostimulatory cells, resulting in survival through T-cell-mediated anti-tumor immunity." (PMID 30282948, 2018). "In the type 1 fusion, these results indicated that the UPR, including the expression of XBP1, played a significant role in the tumor activities of ES cells." (PMID 29581854, 2018). "Human TNBC cells injected into mice developed resistance to doxorubicin and paclitaxel treatment over time but XBP1 knockdown prevented tumour recurrence." (PMID 30248920, 2018). "The present and previous findings therefore show that IRE1α-XBP1 inhibitors exert acceptable anti-tumor activities against malignant tumors." (PMID 29581854, 2018). "We also verified the anti-tumor activities of other IRE1α-XBP1 inhibitors, including STF, HNA and 3ETH, in ES cell lines." (PMID 29581854, 2018). "These in vitro experiments have provided mechanistic insight into how IRE1 can become activated in TNBC and how XBP1 can drive tumour progression through direct interaction with other transcription factors, and through modulation of the tumour secretome." (PMID 30248920, 2018). "Altogether, this work provides evidence indicating that ex-vivo activation of the IRE1α/XBP1 pathway in BMDCs enhances CD8+ T cell specific responses against tumor antigens." (PMID 30687308, 2018). "The present results are of clinical relevance because DCs in tumor milieus show an activation of XBP1 that blunts the immune response and favors tumor cell progression." (PMID 28674530, 2017). "Recent studies have demonstrated that XBP1 deficiency induces defects in eosinophil differentiation and functions of CD8+ and tumor-associated dendritic cells, indicating that spliced XBP1 plays a critical role in development and function of immune cells." (PMID 29097726, 2017).
tumor (continued). "Among these, we have identified miR-125a-3p and miR-320c as potential tumor suppressor microRNAs as they were predicted to target MM-associated oncogenes; IRF-4, XBP-1 and BLIMP-1." (PMID 28664185, 2017). "More recently, XBP1 was demonstrated to foster triple negative breast cancer progression by cooperating with HIF1α to support tumor-initiating cell function and metastatic capacity under hypoxia." (PMID 28105371, 2017). "In breast cancer, the UPR mediator XBP1 was found to facilitate EMT (epithelial-to-mesenchymal transition) promoting tumour invasion." (PMID 26927180, 2016). "XBP1 interacts with hypoxia-inducible factor 1-alpha (HIF1α) in triple negative breast cancer and drives tumor progression by inducing hypoxia signature gene expression." (PMID 27303918, 2016). "Targeting this arm using toyocamycin, a small molecule drug inhibiting IRE1α kinase activity and XBP1 splicing, profoundly inhibits both LNCaP and VCaP cell growth in vitro as well as tumor formation in vivo." (PMID 27303918, 2016). "Transgenic mice studies have shown that XBP-1 splicing occurs during primary tumor growth in a number of breast cancer models." (PMID 25864123, 2015). "Several reports have indicated that the IRE1α signaling, especially via the IRE1α-XBP1 pathway, is required for tumor growth and survival during hypoxia." (PMID 25941664, 2015). "In current studies, we further evaluated XBP1-CTL post-lenalidomide treatment for their specific anti-tumor activity by measuring IFN-γ production and granzyme B expression against the respective HLA-A2+ solid tumor cells." (PMID 27668268, 2015). "For example, the IRE1α-X-box-binding protein 1 (XBP-1) pathway has been shown to promote tumor growth in xenograft models and loss of XBP-1 sensitized cells to death from oxidative stress." (PMID 25864123, 2015). "The accumulating evidence clearly indicates that increasing ER function through UPR, particularly through the IRE1α/XBP1 pathway, is critical for oncogenesis by adapting tumor cells to ER stress and the secretion of growth factors." (PMID 26254280, 2015). "We found that xbp-1 inactivation, not only induced germ cell transdifferentiation but also suppressed the germline tumor; demonstrating that the two phenomena are tightly correlated." (PMID 26192965, 2015). "With the rationale of targeting XBP1 for selective cancer cell killing, we have previously shown that immunogenic heteroclitic XBP1 peptides can evoke antigen-specific CTL with anti-tumor activities against MM cells and various solid tumor cancers." (PMID 27668268, 2015). "The IRE1α/XBP1 transduction axis clearly contributes in tumor development, which is consistent with its reported role in mediating the adaptive response to ischemia." (PMID 26325176, 2015). "The anti-tumor response of XBP1-CTL was further investigated within the CD45RO+ memory or CD45RO− non-memory CD3+CD8+ T cell populations in response to the respective tumor cell lines." (PMID 27668268, 2015). "To determine if other arms of the Unfolded Protein Response (UPR) were activated in addition to PERK, we performed qPCR on RNA isolated from normal muscle and tumor for spliced XBP1." (PMID 26123823, 2015). "Taken together, XBP1 is up-regulated and has a pro-tumor effect in OS with activation of PI3K/mTOR signaling." (PMID 26633383, 2015). "The mRNA level of XBP1 correlated with advanced clinical stages, high degree of malignancy, and low tumor necrosis rate in OS patients." (PMID 26633383, 2015). "High levels of XBP1 correlated with advanced clinical stages, high degree of malignancy, and low tumor necrosis rate in OS." (PMID 26633383, 2015). "The UPR pathway mediated by activation of IRE1 and its downstream target XBP1 is also required to counteract hypoxic conditions leading to tumor growth." (PMID 26491226, 2015). "Elevated levels of XBP1 splicing have been observed in various types of tumor and predict poor outcomes for patients." (PMID 26622781, 2015).
tumor (continued). "In a recent letter to Nature, Chen and colleagues provided intriguing data to show that XBP1 acts as a tumor driver that is required for oncogenesis and cancer stem cell phenotypes associated with TNBC." (PMID 25927911, 2014). "We first confirmed the influence of Tg treatment on the ER stress response in HER2/CT26 tumor cells by measuring ER stress-induced XBP1 mRNA splicing." (PMID 25514597, 2014). "Deletion of XBP1 was found to increase sensitivity to hypoxia-induced cell death and reduce tumor formation." (PMID 24705207, 2013). "To further verify a potent role for the miR-214/XBP-1 pathway in mediating tumor cells survival and in regulating HCC tumor growth, we re-expressed XBP-1 in miR-214 treated HCC cells." (PMID 22359598, 2012). "K14-cre; ApcCKO/+ tumors also expressed genes that are strongly expressed in human luminal tumors, such as XBP1 and luminal cell marker K8 and K18, but were low in basal tumor-defining genes." (PMID 19197353, 2009). "Recent studies have uncovered several functions for XBP-1 and have implicated XBP-1 overexpression in human carcinogenesis and tumor growth under hypoxic conditions." (PMID 17418411, 2007). "A distinguishing feature of these tumors (in particular Group VI) was the high expression of XBP1, which is a human luminal tumor-defining gene." (PMID 17493263, 2007). "Furthermore, the spatial pattern between XBP1 and SPINT2 aligns with previous findings, which identify SPINT2 as a hub gene for tumor and intermediate regions, while XBP1 is a hub gene in the tumor region only." (PMID 39954675, 2025). "Moreover, these PNOC-expressing B-cells upregulate the key transcription factor XBP1, which is essential for B cell fate decisions (germinal center vs. plasma cell) and the generation of high-affinity, tumor-targeting antibodies." (PMID 40951290, 2025). "To determine whether KPC tumor derived factors are responsible for the up-regulation of the IRE1α/XBP1 axis in skeletal muscle, we studied the effect of KPC conditioned medium (KPC-CM) on the levels of IRE1α and sXBP1 in cultured primary myotubes." (PMID 40655023, 2025). "Pharmacological inhibition of IRE1α/XBP1 axis attenuates KPC tumor-induced muscle wasting." (PMID 40655023, 2025). "This strategy paves the way for new immunotherapies targeting XBP1, with the potential to improve prognosis in ovarian cancer and other aggressive tumors, by simultaneously reducing tumor cell survival and restoring an effective antitumor immune microenvironment." (PMID 40278350, 2025). "Using UCSC genome browser, we first analyzed the presence of conserved sXBP1 binding sequences CCACG-box, UPR element (UPRE)-A, or UPRE-B motifs in the promoter region of genes whose expression is affected by the deletion of XBP1 in skeletal muscle of KPC tumor-bearing mice." (PMID 40655023, 2025). "To understand the effect of targeted deletion of XBP1 on KPC tumor-induced muscle atrophy, we next generated transverse sections of TA (fast/glycolytic) and soleus (slow/oxidative) muscle, performed anti-laminin and DAPI staining or H&E staining, followed by morphometric analysis." (PMID 40655023, 2025). "We investigated whether IRE1α/XBP1 axis has any role in fatty acid oxidation in skeletal muscle of KPC tumor-bearing mice." (PMID 40655023, 2025). "Lipid peroxidation, through metabolites such as 4-hydroxynonenal (4-HNE), induces ER stress and constitutively activates the IRE1α–XBP1 signaling axis, promoting aberrant lipid accumulation in tumor-infiltrating dendritic cells (tDCs) and impairing antigen presentation." (PMID 40723802, 2025). "However, there was a modest but significant reduction in the number of KPC cells by day 5 of 4μ8C treatment suggesting that inhibition of the IRE1α/XBP1 signaling can potentially inhibit KPC tumor growth in vivo." (PMID 40655023, 2025).